CD22 (CD22 molecule)
Diseases named in the same sentence as CD22 in open-access papers (continued):
Sharing a sentence is not in itself a finding about the gene and the disease.
tumor (continued). "In these studies, accumulation of cPAM4 within the CaPan1 tumor-bearing mice was 2.8-fold higher than nonspecific hLL2 (anti-CD22 antibody), with peak levels of cPAM4 occurring on day 4 after injection." (PMID 24818166, 2014). "Flow cytometry to determine the immunophenotype of the tumor cells typically demonstrates the expression of B-cell associated antigens (CD19, CD20, and CD22), CD45, and CD30 (weak) and an absence of surface immunoglobulins, CD5, and CD10." (PMID 24194994, 2013). "In contrast, no CD22+CD3− tumor cells were detected using iC9-CD20CAR-Δ19 T cells as effector cells, suggesting complete CD20-specific elimination of tumor cells was achieved." (PMID 24358223, 2013). "In contrast, the CD19 CAR or CD22 CAR alone failed to control the tumor burden." (PMID 38823002, 2025). "Interestingly, compared to the control group, FCM analysis at 96 h showed that pretreatment of tumor cells with rituximab did not significantly upregulate CD19/CD22 CAR-T surface exhaustion molecules (PD-1, TIM-3)." (PMID 38662336, 2024). "Since former studies have found SIGLEC1 (CD169), SIGLEC2 (CD22), SIGLEC3 (CD33), SIGLEC7, SIGLEC9, and SIGLEC15 expressed by immune cell populations could be manipulated by tumor cells to escape immune surveillance, we focused on the five SIGLEC family members." (PMID 33240817, 2020). "This might explain why most progress has been made so far in the clinical development of antibody toxins that target cell surface molecules such as CD22 and CD25 expressed on certain malignancies of hematologic origin, where tumor cells are usually more accessible." (PMID 16168106, 2005). "In addition, compared with CD19 CAR-T, CD22 CAR-T has weaker expansion ability and shorter persistence, so the insufficient activity of CD22 CAR-T may not be able to inhibit the growth of tumor cells." (PMID 36949487, 2023). "The cytotoxic activities of CD22 CAR‐T cells were tested against three CD22‐positive tumor cell lines (Raji, Daudi, BV173) and one CD22‐negative cell line (K562)." (PMID 35665369, 2022). "The CD138+CD3+ tumor cells also expressed high levels of IGHM, CD27, and XBP1, but were absent of CD19, CD22, CD24, and CD10 expression." (PMID 36494694, 2022). "TRACCAR T cells were robustly detected at the CD22(+) tumor site (left flank) but were almost absent from the CD22(-) tumor site (right flank), indicating that TRACCAR T cells preferentially accumulate at their intended tumor-specific site." (PMID 31723132, 2019). "In 22 dogs in which flow cytometry was performed, tumor cells in 15 dogs lacked expression of T (CD3, CD5) or B (CD21, CD22) cell markers." (PMID 28620611, 2017). "Finally, it may be possible in the future to reconstitute the expression of DAPK1 in patients lacking this important tumor suppressor as delivery of its constitutive kinase domain via a CD22-specific immunoligand has shown remarkable in vitro efficacy and selectivity in preclinical testing." (PMID 27610206, 2016). "RC cells had the following immunophenotype: positive for CD10, CD19, CD20, CD22, CD38, CD43, CD44, and CD79b and negative for CD3, CD4, CD5, CD8, CD11c, CD14, CD30, CD56, and CD200, which was identical to the primary tumor cells." (PMID 26515759, 2015). "Similarly, bicistronic CD19/CD22 CAR-T cells in pediatric leukemia showed no severe CRS or neurotoxicity, suggesting that dual targeting can maintain anti-tumor efficacy while curbing inflammatory overload." (PMID 41348261, 2025). "The success of CD22 CAR-T may be due to the resistance of tumor cells to CD19 CAR-T at this time, but not to CD22 CAR-T." (PMID 36466893, 2022). "We noted that CD22 and CD138 expression was not changed by MFI measurement, suggesting that while some cells downregulated expression of these markers during tumor development it was on a per cell basis, and not a phenomenon that globally applied to the entire cell population." (PMID 30265712, 2018).
cancer (66 papers, 2013 to 2026). A tumor composed of atypical neoplastic, often pleomorphic cells that invade other tissues. "Heatmap and functional annotation indicated that several significantly upregulated genes (CCL21, H2‐Eb2, Pax5, CD19, CD22, etc.)were associated with anti‐cancer immunity." (PMID 41306557, 2025). "The new generation 24 kDa PE, which lacks all but the furin-cleavage site of domain II, was mutated at lysine 590 (K590) and at K606 in a CD22-targeting immunotoxin and activity was determined against various B cell malignancies in vitro and in vivo." (PMID 35919491, 2022). "CD20+CD22+ADAM28+ BIR cells were present in cancer-associated TLS and promoted the response to ICI therapy." (PMID 35634306, 2022). "In the context of cancer, especially in certain types of B cell leukemias and lymphomas, CD22 is of particular interest because it can be overly expressed." (PMID 38881902, 2024). "The location of CD22 is on the cell membrane which indicates that it is a good target for treating cancer by CAR-T or CAR-NK cell therapy, preventing off-target effects." (PMID 37817249, 2023). "To date, several clinical investigations are assessing the safety and antitumor efficacy of CD19/CD20- or CD19/CD22-redirected CAR-Ts for the treatment of individuals with blood-based cancers (NCT03233854, NCT03019055, and NCT03196830)." (PMID 36875091, 2023). "CD22 highly expressed various type cancer cells and it can be selectively targeted by Sigleic–2 glycan." (PMID 37344853, 2023). "For example, a significant percentage of B leukemia patients infused with CD22 CAR T cells relapses from the treatment despite a residual expression of CD22 by cancer cells." (PMID 32620049, 2020). "Targeting CD22, therefore, presents a promising strategy for cancer immunotherapy." (PMID 38881902, 2024). "Therefore, increased levels of soluble CD22 are promising biomarkers of various disorders, including cancer, infections, and neurogenerative disorders." (PMID 38711503, 2024). "Another valid study on haematological malignancies focused on bispecific CD19-CD22-CAR-T cells, which were shown to specifically target CD19+ and CD22+ human leukemic cells, generate interferon (IFN)-, and efficiently eradicate the target cancer cells in immune-deficient mice." (PMID 39596267, 2024). "Cluster of differentiation (CD) markers such as CD79b, CD45, CD23, CD22 and CD81 serve as reliable prognostic indicators in CLL as well as the human leukocyte antigen (HLA) with its well-documented associations with various cancers." (PMID 39329950, 2024). "The study also indicates that CD22 CAR-NK cells could be used in other cancers and more in vivo experiments are needed." (PMID 37817249, 2023). "More recent exploration of the cancer engulfment hypothesis has uncovered additional pathways including calreticulin, CD22, and CD24 that intersect with or run parallel to the SIRPα-CD47 pathway and are also potential targets in cancer." (PMID 36459066, 2023). "As CD22 localizes to the cell surface, it might be a useful biomarker, especially in the diagnosis of advanced-stage cancer, and a potential target for CAR therapies in TNBC." (PMID 36768478, 2023). "Significantly, synthetic bryostatin 1 and analogs SUW201 and SUW229 upregulated CD22 surface expression by ~2-fold in each cell line tested, further highlighting the potential generality of using PKC modulators for enhancing CD22-targeted cancer immunotherapies." (PMID 32312992, 2020). "Likewise, anti-cancer agents, including IL-2 + imatinib mesylate (three studies) and anti-CD22 mAb (four studies) showed a dose-dependent increase in the incidence of CLS." (PMID 30691103, 2019). "Also, anti-cancer agents, including IL-2 + imatinib mesylate (three studies) and anti-CD22 monoclinal antibodies (mAb) (four studies), showed a dose-dependent increase in the incidence of CLS." (PMID 30691103, 2019). "Recent research shows that CD22 is a potential drug target in many cancers." (PMID 23737722, 2013).
cancer (continued). "Hence, CD22-targeted delivery of chemotherapy using cancer-specific high-affinity glycans may have clinical potential." (PMID 41154421, 2025). "Interestingly, ESCC patients with different CD22 expression levels had statistically significant differences in lymph node metastasis (p < 0.05, p = 0.008), suggesting that CD22 may promote cancer cell lymph node infiltration." (PMID 37817249, 2023). "Other targets, including TNF receptor superfamily member 17 (TNFRSF17), CD22, CD38, CD33, and C-type lectin domain containing 14A (CLEC14A), demonstrated consistent but lower targeting potential across cancers." (PMID 39439803, 2024). "Among those CAR-T therapy clinical trials that aim to investigate such products for the treatment of patients with blood-based cancer, CD19, CD20, CD22, and BCMA are the most frequent target antigens." (PMID 36875091, 2023). "With regard to B cells, changes included decreases in the gene expression of CD19, CD22, CD72, IKZF3 and GCSAM in cancer patients compared to healthy donors." (PMID 28936253, 2016). "We further identify SIGLEC-1,15 and CD22 as hub genes in COAD through Differentially Expressed Genes (DEGs), which is consistent with our PCA-identified key components PC-1,2,5 considering both the correlation with cancer status and immune cell abundance." (PMID 38650859, 2024). "Moreover, we demonstrate that GoF C2 acts in concert with other therapeutic mAbs, such as type II anti-CD20, anti-CD22, and anti-CD38 specimens, for overcoming cancer cells resistance to complement attack." (PMID 35267578, 2022). "Hence, combined with the results of PRECOG and survival analysis, it implied that the high expressions of CD20, CD22, CD79B, and ADAM28 might predict a positive response to anti-PD-1 immunotherapy for pan-cancer patients." (PMID 35634306, 2022). "While treatment for CD19-negative relapsed cancer after CART19 therapy may be achieved through subsequent administration of CD123 or CD22 CAR T cells, this is not without significant financial costs and safety risks." (PMID 30984613, 2019). "In other clinical studies assessing CD19/CD22 tandem CAR T-cells, some patients relapsed with cancer cells that were negative for CD19, while CD22 expression was conserved or diminished." (PMID 40416955, 2025). "In rare cases, disease relapse results in cancer cells no longer expressing the antigen targeted by CAR-T therapy (CD19 and/or CD22)." (PMID 35328487, 2022).
hematological malignancies (28 papers, 2015 to 2025). "This study is the latest to systematically review the efficacy of CD19 combined with CD22 or CD20 CAR T-cells for the treatment of hematological malignancies." (PMID 40433368, 2025). "The overall OS rate for hematological malignancies treated with CD19 combined with CD22 or CD20 CAR T-cell therapy was 77.9% (95% CI: 69.3–86.6)." (PMID 40433368, 2025). "The overall ICANS rate of CD19 combined with CD20 or CD22 CAR T-cell therapy for hematological malignancies was 11.5% (95% CI: 5.1–19.8)." (PMID 40433368, 2025). "CD20 and CD22 CAR-T immunotherapies have achieved good results in hematological malignancies, including cases in which patients have previously received CD19 CAR T-cell therapy." (PMID 40433368, 2025). "The overall CRS rate of CD19 combined with CD22 or CD20 CAR T-cell therapy for hematological malignancies was 56.8% (95% CI: 42.2–70.9)." (PMID 40433368, 2025). "The data from this study suggest that CD19 combined with CD22 CAR T-cell therapy had a higher partial response rate in the treatment of hematologic malignancies and higher safety profile in the occurrence of ICANS than CD19 combined with CD20." (PMID 40433368, 2025). "The aim was to compare the efficacy and safety of CD19 combined with CD22 with that of CD19 combined with CD20 CAR T-cell therapy in the treatment of hematological malignancies, so as to provide an evidence-based reference for research." (PMID 40433368, 2025). "CD19 combined with CD22 or CD20 therapy is a promising immunotherapy approach for the treatment of hematological malignancies." (PMID 40433368, 2025). "According to subgroup analysis, the PR of CD19 combined with CD20 in the treatment of hematological malignancies was lower than those of CD19 combined with CD22." (PMID 40433368, 2025). "This study synthesized the current evidence on combined therapy with CD19 and CD20 or CD22 CAR T-cells and compared the efficacy and safety of combining CD19 with CD20 or CD22 CAR T-cells for the treatment of hematological malignancies." (PMID 40433368, 2025). "The trial NCT02903810 was planned with a treatment scheme of infusion of equal numbers of anti-CD19 and anti-CD22 CAR-T cells in the treatment of refractory hematologic malignancies." (PMID 29058636, 2017). "We here report on the development of ADCs with specificity for the B-cell lineage specific (surface) antigen CD22 being expressed in the majority of hematological malignancies." (PMID 26605343, 2015). "The OS rate for hematological malignancies treated with CD19 combined with CD22 CAR T-cell therapy (78.7%, 95% CI: 66.8–90.7) was greater, although not significantly, than that for hematological malignancies treated with CD19 combined with CD20 CAR T-cell therapy (76.8%, 95% CI: 69.6–84.0)." (PMID 40433368, 2025). "Like naked Abs, ADCs, and BiTEs, CARTs target CD19, CD20, and CD22 in hematological malignancies." (PMID 39518937, 2024). "Besides this, CD22 CAR-T cell therapy has been shown to be effective against hematological malignancy in previous clinical studies." (PMID 37817249, 2023). "For example, in the treatment of hematological malignancies, one of the main potential toxicities produced by CD22 as a CAR-T target is cytokine release syndrome (CRS), and the drug tocilizumab (approved by FDA) is being extensively used to deal with CRS, which can block the activity of cytokines." (PMID 36768478, 2023). "Aside from the CD19 antigen, VHH-based CAR-Ts could also be used for the simultaneous targeting of other hematologic malignancy-associated target antigens such as CD20, CD22, CD123, CD30, etc." (PMID 36875091, 2023). "This type of strategy could also be applied to hematological malignancies via the use of a bispecific adaptor targeting CD19 or CD22." (PMID 36248810, 2022).
hematological malignancies (continued). "In summary, our findings indicate that the combination of CD19 with either CD22 or CD20 CAR T-cell therapy yields a substantial and enduring clinical response in patients afflicted with hematological malignancies." (PMID 40433368, 2025). "Currently approved targets of ADCs in hematological malignancies are CD19, CD22, CD30, CD33, and CD79b." (PMID 39518937, 2024). "A case report has described the use of CD19-CAR-T cells with membrane-bound IL-15 for B-ALL (following CD19- and CD22-CAR-T cell therapy failure), demonstrating such IL-15-expressing CAR-T cells can be applied to hematological malignancies." (PMID 36248810, 2022). "Currently, most approaches are based on well-established targets adapted from CAR-T cells, including CD19 and CD22, and CAR-NK cells against these targets are being investigated in clinical trials for hematological malignancies." (PMID 34374809, 2022). "CD20, CD22, and BCMA are also frequently studied targets in CAR T-cell therapy for hematologic malignancies." (PMID 32999455, 2021). "Immunotherapies with mAbs specific to CD19, CD20, CD22, CD38, as well as chimeric antigen receptor (CAR)-modified T cell therapy, have recently revolutionized the treatment of hematological malignancies." (PMID 32806528, 2020). "For the treatment of hematologic malignancies several other ADCs, targeting CD79b, CD74, CD33, CD30, CD22, and CD19, are currently in clinical development." (PMID 26605343, 2015). "A total of 13 studies that met the criteria were selected, including 8 studies on the treatment of hematological malignancies with CD19 combined with CD22 CAR T-cell therapy and 5 studies on the treatment of hematological malignancies with CD19 combined with CD20 CAR T-cell therapy." (PMID 40433368, 2025). "For this proof of concept, two different CARm-encoding CAR tool constructs specific for antigens that are expressed in hematological malignancies (tool CAR123 and tool CAR22, which are specific for CD123 and CD22, respectively) were used to assess the robustness of our engineering strategy." (PMID 35773273, 2022). "In addition, CD22, CD20, and CD123 are frequently studied targets in CAR T therapy for hematologic malignancies." (PMID 32999455, 2021). "We also discuss the basic research and ongoing clinical trials on emerging immune checkpoints (Galectin-9/Tim-3, CD70/CD27, LAG-3, and LILRBs) and on new targets for CAR-T cell therapy (CD22, CD33, CD123, BCMA, CD38, and CD138) for the treatment of hematologic malignancies." (PMID 31186046, 2019).